CDK9 (cyclin dependent kinase 9)
Diseases named in the same sentence as CDK9 in open-access papers (continued):
Sharing a sentence is not in itself a finding about the gene and the disease.
cancer (continued). "While the impact of CDK9 on gene regulation has been explored to a lesser extent, emerging reports suggest CDK9 is crucial to the expression of pro-survival genes and maintaining stem-cell-like features of cancer cells." (PMID 41505030, 2026). "Given this intricate relationship, we hypothesized that CREPT might influence cancer cell sensitivity to CDK9 inhibitors (CDK9i), potentially impacting therapeutic efficacy." (PMID 40860160, 2025). "The anti-carcinogenesis effect demonstrated in 4-NQO-induced mouse models of oral mucosal carcinogenesis using CDK9 inhibitor could prove transformative if translated into clinical trials for preventing cancers in precancerous conditions." (PMID 41360777, 2025). "Genomic alterations in the CDK9 gene are relatively uncommon in human cancers." (PMID 39800748, 2025). "In this study, a series of dual CDK9/HDACi based on N-(2-aminophenyl)-5-(4-aryl-pyrimidin-2-yl)amino-1H-indole-2-carboxamide scaffolds was designed and synthesized to target transcriptional dysregulation in cancer." (PMID 41440016, 2025). "Targeting CDK9 in cancer has yielded promising results in both preclinical and clinical studies." (PMID 40492119, 2025). "CDK9 also promotes several other key oncogenic signaling pathways in cancer." (PMID 39117800, 2024). "There is also evidence that CDK9-driven phosphorylation has been known to promote many cancers." (PMID 38534727, 2024). "Owing to these essential regulatory functions, it is no surprise that dysregulation of CDK9 and other CDKs is closely associated with cancer progression." (PMID 38769311, 2024). "Targeting the CDK9/ERK/MYC network in cancer cells, as well as their crosstalk with the TME via the complement system may yield improved responses in KRAS‐mutant patients." (PMID 39254172, 2024). "Among these, AZD-4573 is a highly selective CDK9 inhibitor that induces cancer cell apoptosis and cell death via MCL-1 depletion, thus showing promising preclinical in vivo efficacy, both as a monotherapy and in combination with Venetoclax, in hematologic cancer models." (PMID 38172923, 2024). "CDK9 inhibition has also been applied in cancers characterized by other oncogenic drivers." (PMID 38172923, 2024). "While the unique anatomic and physiologic considerations for CNS tumors necessitate the selection of appropriate agents for adequate CNS delivery, our data supports the use of clinically-relevant CDK9 inhibitors in a multimodal treatment approach for these lethal cancers." (PMID 38816355, 2024). "Inhibiting CDK9 disrupts transcriptional processes crucial for cancer cell survival and proliferation while modulating CYP3A4 activity could optimize the pharmacokinetics of chemotherapeutic agents, improving their efficacy." (PMID 39498375, 2024). "The potential for overriding CDK9 may lead to the disruption of transcriptional programs that fuel cancer evolution, positioning it as a compelling scheme in pursuing novel anticancer therapeutics." (PMID 38534727, 2024). "The fact that the prognostic value of CDK9 differs between right- and left-sided cancer may support this assumption as both cancer locations differ significantly regarding their genomic background." (PMID 36979907, 2023). "The inhibition of CDK9 is a well-established therapeutic target in cancer therapy." (PMID 37513929, 2023). "Both patients (165 and 89) showed overexpression of CDK9 in cancer tissues." (PMID 36979907, 2023). "Consequently, more attention has been paid to the development and evaluation of selective CDK9 inhibitors in order to target the deregulated cell cycle progression of cancer cells." (PMID 36979907, 2023). "Through kinase selectivity, physicochemical properties, DMPK properties, in vitro and in vivo efficacy, 55 is the first potent and highly selective PTEFb/CDK9 (IC50 CDK9/CycT1: 13 nm, ratio of IC50 values CDK2/CDK9: 100) inhibitor to enter clinical trials for the treatment of cancer." (PMID 37298753, 2023).
cancer (continued). "Furthermore, CTCF has been proposed to regulate CDK9 recruitment at the MYC locus and has been implicated in cancer-specific transcriptional dysregulation." (PMID 36998071, 2023). "Interestingly, by employing a versatile in-vivo target validation platform, it has recently been shown that indeed CDK9 inhibition is not only a promising target in various cancer types, but that it can also be safely applied within a therapeutic window." (PMID 36195672, 2023). "CDK9 inhibition using MC180295 reactivates epigenetically silenced genes in cancer by dephosphorylating the SWI/SNF protein BRG1, leading to the restoration of tumor suppressor gene expression, cell differentiation, and activation of endogenous retroviral genes." (PMID 37272701, 2023). "CDK9 inhibitory activity was experimentally confirmed using LS513 (KRAS G12D), SW620 (KRAS G12V), and Colo320 (RAS WT) tumor cell line models, and demonstrated the effectiveness of this group of molecules in treating cancer harboring KRAS mutations." (PMID 37569406, 2023). "The combination therapy of CDK9 and TRAIL may thus represent a potent combination for selectively targeting cancer cells due to the overexpression of CDK9 and the cancer-exclusive expression of TRAIL receptors." (PMID 36979907, 2023). "A total of 73 patients could be assigned to the first group with a low CDK9 score (mean score = 412) and 102 patients assigned to the high CDK9 score group (mean score = 787) in the carcinoma tissue." (PMID 36979907, 2023). "Clearly, OGT acts at multiple points to enable cancer cells’ adaptive response to CDK9 inhibition." (PMID 35708495, 2022). "However, we verified CRBN and CDK9 expression levels in the described cells using the Cancer Cell Line Encyclopedia database." (PMID 35628286, 2022). "Targeting CDK9 in cancer showed promising results in preclinical and clinical research." (PMID 35884401, 2022). "CDK9 is a potential target that has widely attracted attention in cancer studies." (PMID 36313366, 2022). "Thus, CDK9 is highly expressed in all cancer entities tested and its inhibition represents a valid approach which appears to broadly sensitize tumor cells to TRAIL-induced cell death." (PMID 34535764, 2022). "As shown here for Cdk9, it involves the efficient production of transgenic strains harboring an inducible shRNA capable of suppressing the therapeutic target followed by somatic delivery of elements needed to produce autochthonous genetically defined cancers." (PMID 35442775, 2022). "We hypothesize that in response to the decline in CDK9 activity, cancer cells decrease glucose uptake and ATP synthesis to suppress production of ROS and thereby limit the DNA damage." (PMID 35708495, 2022). "CDK9 is a transcriptional regulator and potential therapeutic target for many cancers." (PMID 35053461, 2022). "We, therefore, conclude that the combination of a TRAIL-receptor agonist with a CDK9-inhibiting drug could potentially serve as an effective therapy for various types of cancers that have developed resistance to current therapies." (PMID 34535764, 2022). "The broad MC180295 anti-cancer activity in-vivo and in-vitro seems promising, although the lack of toxicity and higher selectivity goes hand in hand with relatively lower potency toward CDK9 when compared to AZD-4573." (PMID 35092513, 2022). "However, available literature mentions an ambiguous prognostic role of CDK9, which differs in various types of cancers." (PMID 35326643, 2022). "The anti-cancer activity of the CDK9 inhibitors may be explained through a more complex mechanism than simply decrease in transcription." (PMID 35164752, 2022). "Altogether, CDK9 plays key roles in controlling gene expression through transcription elongation regulation and maintaining epigenetic silencing, representing an interesting target for cancer chemotherapy." (PMID 35884401, 2022). "Moreover, 16 demonstrated remarkable cytotoxicity exclusively against CDK9-overexpressing cancer cells." (PMID 36235168, 2022).
cancer (continued). "This could indicate that CDK7 and CDK9 contribute to cancer cell fitness through regulation of different aspects of the MYC transcriptional network." (PMID 36577800, 2022). "Collectively, these observations suggest that while cancer cells respond similarly, in terms of cell viability in vitro, to the loss of CDK9 and key factors controlling transcription, this is not the case for the majority of tCDKs, including CDK7." (PMID 36577800, 2022). "In our study CDK9 expression was the highest in the low-stage tumors, suggesting that CDK9 overexpression may play an important role in cancer development, but its role decreases when the genomic instability increases." (PMID 35326643, 2022). "On the other hand, the four CDK9 inhibitors have a wide range of effects on cancer cell growth." (PMID 36577800, 2022). "Therefore, CDK9 inhibition depletes antiapoptotic proteins, which in turn leads to the reinstatement of apoptosis in cancer cells." (PMID 36615314, 2022). "However, understanding the mechanism(s) by which CDK9 inhibition contributes to anti-cancer effects is still under investigation." (PMID 35567477, 2022). "Interestingly, across several cancer types the expression levels of CDK9 protein, as analyzed by immunohistochemistry in the human protein pathology atlas, confirmed high CDK9 expression in diverse tumor types." (PMID 34535764, 2022). "The idea that transcriptional programs are highly dysregulated in cancers and that cancers become over-dependent on certain factors that control gene expression has led to increased efforts to inhibit transcriptional CDKs, such as CDK9." (PMID 34207158, 2021). "Designs for future studies might use conditional genetic knockout of the CDK9 or cyclin T1/2 genes in various established cancer models to provide more information about the role of the P-TEFb complex in tumor formation." (PMID 34041038, 2021). "Therefore, there is a need to develop feasible treatment strategies for CDK9-induced malignant tumors." (PMID 34277564, 2021). "Due to the extremely critical role of CDK9 in cancer cells, inhibiting its functions has been the subject of intense research, resulting the development of multiple, increasingly specific small-molecule inhibitors, some of which are presently in clinical trials." (PMID 34062779, 2021). "A total of 339 compounds were tested in a CDK9 assay and cancer cells." (PMID 33632038, 2021). "Cyclin dependent kinase 9 (CDK9) has emerged as a potential target in cancer." (PMID 34830877, 2021). "at AbbVie explored several tetracyclic systems as CDK9 inhibitors for cancer treatment." (PMID 33632038, 2021). "This addiction to transcription makes cancer cells highly susceptible to the inhibition of CDK9 relative to non-transformed cells." (PMID 34041038, 2021). "Moreover, several reports have demonstrated the prognostic value of CDK9 overexpression in various cancers, including OC." (PMID 34011401, 2021). "Cyclin-dependent kinase 9 (CDK9), a core component of P-TEFb, regulates the process of transcription elongation, which is associated with differentiation and apoptosis in many cancer types." (PMID 34372855, 2021). "Indeed, selective genetic and pharmacological inhibition of CDK9 elicits a strong antineoplastic response in hematologic and solid tumor cells in vitro as well as in in vivo cancer models." (PMID 34741018, 2021). "There is a sufficient evidence to support CDK9 as a valid therapeutic target in cancer through promotion of cell proliferation and regulation of anti-apoptotic proteins such as Mcl-1 and Myc that initiate cancer cell immortality." (PMID 33632038, 2021). "CDK9 is an extremely critical kinase in regulating the productive transcription of several anti-apoptotic and oncogenic genes, essential for the maintenance, growth, metastasis and chemo-resistance of cancers." (PMID 34062779, 2021).
cancer (continued). "Therefore, inhibiting MYC transcription indirectly via BET inhibitors or affecting transcription of Myc target genes by inhibiting CDK9 are promising strategies that have shown efficacy in Myc-driven cancers." (PMID 33322239, 2020). "Since BET proteins, CDK7, CDK9, and HDACs, serve as actionable targets in many cancers addicted to CRC, combination of CRC-disrupting agents with either current treatment modalities or novel antitumor compounds may improve therapeutic response." (PMID 32943730, 2020). "Finally, the ability of CDK9 to maintain increased levels of the anti-apoptotic protein MCL1 is considered one of the mechanisms that leads to cancer cell survival and subsequent hematological and solid tumors development." (PMID 32903585, 2020). "We wanted to test the possibility that continuous CDK9 activity could be required to maintain MDM4 expression also in non-cancer cell types." (PMID 32934219, 2020). "Moreover, CDK9 participates to MYC gene transcription in a number of cancer types through the recruitment of P-TEFb to chromatin by the bromodomain-containing protein 4, BRD4, which recognizes the acetylated histone tails." (PMID 32903585, 2020). "Cdk9 in its own right has been considered a promising target in cancer therapy." (PMID 31402912, 2019). "MiR-206 is downregulated during tumorigenesis and plays an important role in modulating the growth of multiple HCC cells via targeting cyclin-dependent kinase 9 (CDK9), which stimulates the production of abundant prosurvival proteins, leading to impaired cancer cell apoptosis." (PMID 31640265, 2019). "Consequently, although therapeutic inhibition of Cdc7 and Cdk9 continues to provide opportunities in cancer, their impact on the immune system warrants further consideration for clinical application." (PMID 31402912, 2019). "Studies on the cancer field have described that BRD4 contributes to the recruitment of the positive transcription elongation factor b (P-TEFb) complex (heterodimer of CDK9 and cyclin T1, T2, or K) to the promoter region and activates RNA polymerase II-dependent (RNAPII) transcription." (PMID 30647531, 2018). "However, phosphorylation of RNA pol II on Ser2 markedly increased in 3D mammospheres, raising the possibility that cellular demand for CDK9 activity is elevated in cancer stem-like 3D mammospheres." (PMID 30647871, 2018). "Taken together, these findings suggest that the function of the two CDK9 isoforms is likely to be at least partially distinct, although further studies are required to produce definitive evidence and importantly in the cancer context, including in AML." (PMID 29471852, 2018). "Mcl-1 and CDK9 inhibitors, however, have had limited success in cancer therapy." (PMID 28520795, 2017). "MSCT-EVs induced pronounced apoptosis in TRAIL-resistant cancer cells and this effect could be further enhanced using a CDK9 inhibitor." (PMID 28326166, 2017). "CDK9 specific inhibitors may be a potential alternative treatment not only of cancer, but also for autoimmune- and inflammatory diseases." (PMID 27511630, 2016). "Because the i-CDK9-induced MYC expression and binding to P-TEFb compensate for P-TEFb's loss of activity, only simultaneously inhibiting CDK9 and MYC/BRD4 can efficiently induce growth arrest and apoptosis of cancer cells, suggesting the potential of a combinatorial treatment strategy." (PMID 26083714, 2015). "Variolin B is in preclinical evaluation for cancer therapeutics, yet meriolins display greater specificity for CDKs than variolin B, especially CDK2 and CDK9 as well as better antiproliferative and proapoptotic features than parental counterparts in human cancer cell lines." (PMID 25625291, 2015). "Future studies regarding the detailed mechanisms of Mcl-1 regulation via CDK9 may help to develop a new targeted therapeutic strategy for cancer." (PMID 26720004, 2015).
cancer (continued). "Based on these results, specific CDK9 inhibitors and identification of a new Bay 61–3606 target for Mcl-1 degradation may be beneficial for the treatment of cancers in which Mcl-1 contributes to the development of resistance to anticancer therapeutics." (PMID 26720004, 2015). "Also known as CYC202 or seliciclib, this purine analog primarily inhibits CDK2 and CDK5, as well as CDK1, CDK7 and CDK9 in several forms of human cancers." (PMID 25625291, 2015). "The CDK9-related pathway has emerged as a target of extreme for cancer therapy." (PMID 23840966, 2013). "In this review, we discuss recent findings provided by structural biologists that may allow further development of highly specific inhibitors of CDK9 towards applications in cancer therapy." (PMID 22571657, 2012). "Upregulation of HSP70 by ML346 induced cell paraptosis in a CDK7/CDK9-dependent manner, while selective inhibition of HSP70 by 2-phenylethynesulfonamide impaired the function of associated chaperones and resulted in cell paraptosis in several cancer cell lines." (PMID 38858714, 2024). "Therefore, elucidating the cellular compensation triggered by CDK9 inhibition in solid tumors may markedly potentiate the effectiveness of this potent intervention in highly refractory cancers." (PMID 39254172, 2024). "Furthermore, enhanced CDK9-mediated transcription elongation increases the expression of prosurvival and antiapoptotic proteins, such as c-Myc, Mcl-1, and survivin, thereby contributing to the proproliferative and antiapoptotic phenotype of cancer cells." (PMID 35088192, 2023). "Therefore, the specific delivery of CDK9 degraders to cancer cells could open up the possibility of using this compound in cancer treatment." (PMID 37272701, 2023). "Thus, the combination of optimized TRAs with CDK9 inhibitory drugs, of which many are under clinical evaluation, may bear the potential to bypass therapy resistance in many types of cancer." (PMID 36195672, 2023). "Thus, the degradation of CDK9 or the inhibition of kinase activity may restore the ability of cancer cells to undergo apoptosis." (PMID 36986673, 2023). "Similarly, the CDK2/CDK9 inhibitor CYC065 (Cyclacel) was found to induce mitotic catastrophe in CIN+ cancer cells, restraining tumour growth and underscoring its potential to treat cancers that display high-grade aneuploidy and substantial intratumoural karyotype heterogeneity." (PMID 38067140, 2023). "In addition to changes in CDK9 expression or activity, CDK9/P-TEFb-related regulators may also be involved in CDK9-related diseases (e.g., cancers)." (PMID 35088192, 2023). "According to this hypothesis, in cancers with a relatively lower frequency of somatic mutations, the expression of CDK9 is not hindered by genomic instability and high CDK9 expression may predict a poor prognosis." (PMID 35326643, 2022). "CDK9 is overexpressed in various solid and hematological malignancies, where CDK9 is the principal regulator that stimulates transcriptional elongation, through which short-lived antiapoptotic proteins (e.g., Mcl-1) are overexpressed, leading to cancer cells becoming resistant to apoptosis." (PMID 36615314, 2022). "Therefore, whereas both CDK7 and CDK9 may contribute to cancer cell fitness through differential interactions with the MYC network, they display clearly specialized relationships with other signaling pathways relevant for cancer development." (PMID 36577800, 2022). "However, a more rigorous assessment of Caspase-8 expression and the corresponding stratification of patients will be of utmost importance in determining the clinical success of the CDK9-based targeted strategies in cervical and other cancer entities in the future." (PMID 36399280, 2022).